NGF (nerve growth factor)
Diseases named in the same sentence as NGF in open-access papers (continued):
Sharing a sentence is not in itself a finding about the gene and the disease.
neuroblastoma (continued). "C3G is phosphorylated in response to forskolin and NGF and TC-PTP expression inhibited forskolin induced differentiation of neuroblastoma cells dependent on its catalytic activity." (PMID 21876762, 2011). "IFRS1 cells retain an intrinsic ability to myelinate neurites in co-culture with primary cultured adult rat DRG neurons, nerve growth factor (NGF)-primed PC12 cells, mouse embryonic stem (ES) cell line-derived motor neurons, and the mouse neuroblastoma/mouse motor neuron hybrid NSC-34 cell line." (PMID 41002926, 2025). "Moreover, in human neuroblastoma SH-SY5Y cells, application of media from IPA-treated microglia enhanced BDNF and nerve growth factor synthesis." (PMID 40942152, 2025). "Mainly, nerve growth factor (NGF), neurotrophin-7, and neurotrophin-6 bind to TrkA, and activation of TrkA triggers various signaling pathways involved in cell survival, differentiation, and growth, particularly in neurons and neuroblastomas." (PMID 39124968, 2024). "They demonstrated different effects of NGF on neuroblastoma cell survival: it decreased proliferation of a p75NTR, but not TrkA-expressing neuroblastoma clone, while an increasing proliferation effect was found in other clones." (PMID 39056738, 2024). "If added to human neuroblastoma cells, Milmed yeast promoted the expression of BDNF and NGF mRNAs." (PMID 36551872, 2022). "In our previous report, we showed that Milmed yeast addition to human SK-N-SH neuroblastoma cells promoted the expression of BDNF and NGF, confirming that Milmed co-treatment may be suitable for several neurologic and neuropsychiatric disorders." (PMID 36551872, 2022). "In one study similar to NGF, NMB administration prolonged the survival of the neuroblastoma cell line SH-5Y, although it did not promote neuron-like differentiation of these cells, whereas NGF did." (PMID 34539578, 2021). "β-caryophyllene was shown to activate trkA receptors (involved in regulating synaptic strength and plasticity in the nervous system) and induce neuritogenesis in PC12 and SH-SY5Y neuroblastoma cells without affecting nerve growth factor (NGF) or CB2 receptors." (PMID 33915950, 2021). "In line with this, the N-terminal human sequence 1–14 (hNGF1–14) and its acetylated derivative Ac-hNGF1–14 demonstrated a good NGF-like in vitro activity by protecting PC12 cells from NGF withdrawal driven degeneration as well as neurotrophic signalling in PC12 and neuroblastoma cell lines." (PMID 32024191, 2020). "Carnosine also induced expression of the brain-derived neurotrophic factor (BDNF) and nerve growth factor (NGF) in a human primary glioblastoma cell line (but not neuroblastoma)." (PMID 31141890, 2019). "p75 transfected into human neuroblastoma cells (negative for p75) induced high-affinity binding of NGF and cell differentiation in response to NGF." (PMID 29175861, 2018). "Okadaic acid has been shown to inhibit neurite outgrowth in NGF-treated PC12 cells at low nanomolar concentrations, and in cultured rat cortical neurons and the human neuroblastoma cell line MSN, okadaic acid induced changes in neuronal cytoskeleton that led to cell death." (PMID 28583171, 2017). "Nerve Growth Factor (NGF), Insulin-like Growth Factor (IGF), Epidermal Growth Factor (EGF), Platelet-Derived Growth Factor (PDGF) and Vascular Endothelial Growth Factor (VEGF) are major growth factor signalling pathways in Neuroblastoma." (PMID 26010602, 2015). "Experiments were conducted by using several types of neuronal cells, including transformed cell lines (NGF-treated Rat PC12, NGF-preprimed PC12, human SY5Y neuroblastoma) and freshly isolated primary cells (mouse cerebellar granule neurons, mouse hippocampal neurons, rat hippocampal neurons)." (PMID 24562333, 2014).
neuroblastoma (continued). "The authors continued to presume that the NGF/NTRK1 interaction contributed to differentiation in vivo, since defects in the NTRK1 receptor pathway of the employed cell lines hampered comparison with processes in less aggressive maturing neuroblastomas." (PMID 25361003, 2014). "Paracrine communication within this complex tumor are certainly not limited to the NRG1 and NGF effector molecules with the NTRK1 receptor, since the immune system and angiogenic tumor supply also contribute to overall neuroblastoma clinical presentation and aggressiveness." (PMID 25361003, 2014). "On the other hand, NGF promotes apoptosis in human SK-N-MC neuroblastoma cells expressing nerve growth factor receptor (p75NTR/NGFR) but not TRKA; however, it does not cause the death of human IMR32 neuroblastoma cells expressing TRKA but not p75NTR." (PMID 41189817, 2025). "Activation of this neurotrophin receptor by its ligand nerve growth factor initiates a cascade of signaling events leading to neuronal differentiation of TRKA-expressing cells in vitro, and elevated TRKA expression is characteristic of biologically favorable neuroblastoma." (PMID 38691450, 2024). "In addition, in vitro NAC interfered with the activation of TrkA by NGF in SH-SY5Y neuroblastoma cells at millimolar concentrations not affecting cell viability (up to 20 mM)." (PMID 38203377, 2023). "It has been recently reported that DLG2 plays an important role in the nerve growth factor (NGF)-induced differentiation through the regulation of its receptor TrkA expression via positive feedback interactions between TrkA and DLG2 in human neuroblastoma cells." (PMID 35966008, 2022). "On the other hand, Aβ mediated cell death via p75NTR is altered by the NGF, the NGF binding instead of Aβ inhibits the p75NTR death signalling, however, the Aβ-p75NTR induced death is found in PC12 cells, NIH 3T3 cells, human neuroblastoma cells and hippocampal neurons." (PMID 34572312, 2021). "Finally, using neuroblastoma cells deficient in endogenous GM1, it has been demonstrated that NGF did not elicit the autophosphorylation of the Trk protein, but the rescue of GM1 content recovered the responsiveness of Trk to its ligand." (PMID 32013258, 2020). "Toward this end the neuroblastoma, wild type SH-SY5Y and SH-SY5Y-APP cell lines were incubated with all-trans retinal for 6 days, while the pheochromocytoma wild type PC12 and PC12-htau cell lines were incubated with NGF for 7 days, to enable differentiation to neuron-like cells." (PMID 30971876, 2019). "Many of those pathways were previously published in relation with the severity of neuroblastoma, such as AKT signaling, cAMP- and IP3–dependent signal transduction mechanisms, and also estrogen, growth hormone signaling regulating glucose uptake, MAPK, PPAR, NGF and Ras signaling." (PMID 29137381, 2017). "Interestingly, the expression of HNT is significantly increased in neuroblastoma cell lines that are induced to differentiate using RA (retinoic acid), RA plus BDNF (brain-derived neurotrophic factor), NGF (nerve growth factor) and TPA (12-O-tetradecanoyl-phorbol-13-acetate)." (PMID 16000168, 2005). "Moreover, mangiferin promoted secretion of nerve growth factor (NGF) and tumor necrosis factor (TNF)-α (TNF-α) in human neuroblastoma cells, U138-MG, which suggested that mangiferin increased the level of neurotrophic factors and cytokines and may improve recognition memory." (PMID 31484797, 2019). "Human neuroblastoma SKNMC and human glioblastoma-astrocytoma U373 cells adhered and proliferated preferentially on the PVA/chitosan scaffolds conjugated with NGF in comparison with the controls (positive—nanocomposites without NGF and negative—polystyrene)." (PMID 31861485, 2019).
neuroblastoma (continued). "Mutual interaction of NTRK1-expressing neuroblastomas with Schwann cells via the NRG1/NGF-axis helps to explain both the high Schwann cell infiltration in NTRK1-positive primary neuroblastomas and the absence of Schwann cells in NTRK1-negative neuroblastomas." (PMID 25361003, 2014).
breast cancer (83 papers, 2006 to 2026). A primary or metastatic malignant neoplasm involving the breast. "Nerve growth factor (NGF) has been reported to be a target for such therapy due to the associated overexpression of NGF in breast cancer cells when compared to other tissues such as breast epithelium." (PMID 40563551, 2025). "NGF has also been implicated in the progression of human cancers especially in aggressive breast cancers." (PMID 40371393, 2025). "Nerve fibers infiltrate the tumor microenvironment, which is associated with nerve growth factor production and lymph node invasion in breast cancer." (PMID 37566075, 2023). "The NGF/TrkA pathway has also been implicated in the development and progression of breast cancer and prostate cancer." (PMID 37566075, 2023). "Regarding the molecular subtypes, NGF was positively associated with luminal B and basal-like breast cancer, with a comparable or better specificity than other basal markers or ER, PR, HER2 and Ki67, respectively." (PMID 36354700, 2022). "We previously showed that NGF is implicated in breast cancer aggressiveness because it enhances cell migration/invasion." (PMID 35346305, 2022). "We cloned the Brn-3b promoter, mapped the transcription start site and showed stimulation by estradiol and growth factors, nerve growth factor and epidermal growth factor, which are implicated in breast cancer initiation and/or progression." (PMID 21241485, 2011). "NGF signaling has been implicated in the proliferation and survival of breast cancer cells and more recently, migration." (PMID 24212627, 2011). "The objective of the present study was to better determine the possible involvement of NGF in breast cancer angiogenesis, as well as the underlying molecular mechanisms." (PMID 20569463, 2010). "The objective of the present study was to determine the involvement of nerve growth factor (NGF) in breast cancer angiogenesis and the underlying molecular mechanisms." (PMID 20569463, 2010). "This further indicates that an increase in NGF may be associated with further growth in breast cancer cells, and it has been discovered that effectively diminishing or neutralizing NGF contributed to reduced ability of malignant cell proliferation." (PMID 40563551, 2025). "NGF and its receptor may represent a good diagnostic and prognostic tool and a promising therapeutic target for breast cancer." (PMID 37978384, 2023). "Other studies suggested that NGF and its receptors could represent a good diagnostic and prognostic tool, as well as promising therapeutic targets for breast cancer." (PMID 36354700, 2022). "Other evidence indicates that both NGF and its receptors could be considered accurate diagnostic and prognostic tools for breast cancer." (PMID 36354700, 2022). "Although we were unable to compare exosomal NGF levels in the serum with corresponding tumor tissue, we probed public databases to determine the associations of the NGF-TrkA/p75NTR axis with survival outcomes in patients with breast cancer." (PMID 34771423, 2021). "A high level of peripheral NGF has been shown to be associated with ovarian and breast cancer, polycystic ovarian syndrome (PCOS), and endometriosis, providing evidence for the increased risk of breast and endometrial cancer caused by long-term estrogen replacement therapy." (PMID 31428228, 2019). "In addition, the expression patterns of NGF or TrkA were associated with poor prognosis of tongue cancer, pancreatic cancer, and breast cancer." (PMID 28679437, 2017). "In particular, NGF is produced and released by breast cancer and tumor-associated stromal cells." (PMID 25840418, 2015). "Paracrine/autocrine activation of NGF signaling has been implicated in tumor progression, cell survival and metastasis and deletion or mutation of Cav-1 have been reported for certain cancers, notably breast cancer while overexpression has been observed in certain prostate cancer lines." (PMID 28338624, 2017).
breast cancer (continued). "As previously stated, breast cancer‐targeted PLGA nanoparticles containing siRNA targeting NGF suppress NGF‐mediated proliferation of sympathetic nerves post‐chemotherapy, thereby demonstrating enhanced anticancer efficiency." (PMID 41556039, 2026). "It was worth mentioning that NGF signaling axis had been proven to be involved in resistance to chemotherapy in breast cancer 49-51." (PMID 40612670, 2025). "In vivo IVIS imaging in animal models demonstrated specific binding of NGF to breast cancer (MDA-MB-231) and colorectal cancer (HCT116), with prolonged retention observed up to 72 h." (PMID 40048021, 2025). "The activation of CB1 receptors inhibits nerve growth factor (NGF)-induced proliferation of breast cancer cells in breast cancer." (PMID 41154659, 2025). "In terms of breast cancer, it had been reported that primary breast tumor cells can acquire NGF to promote their survival, proliferation and metastasis in an autocrine/paracrine manner 44-46." (PMID 40612670, 2025). "MDA-MB-231 breast cancer cells secrete NGF, which has been shown to stimulate angiogenesis in vivo when injected into immunodeficient mice." (PMID 38375479, 2024). "Research indicates that in both pancreatic and breast cancer models, blocking the Nerve Growth Factor (NGF) effectively counters tumor invasion and metastasis." (PMID 38567163, 2024). "In another breast cancer study, the NGF was described as a mitogen and stimulated breast cancer cell survival via NGF receptor P140trKA and P75NTR." (PMID 37296923, 2023). "In breast cancer, NGF signaling via TrkA can trigger the proliferation and invasion of cancer cells." (PMID 38049878, 2023). "Previous in vitro experiments have indicated that the cocultivation of human breast cancer cells with rat neurons led to an elevation in the synthesis of NGF by the breast cancer cells." (PMID 38020711, 2023). "It is involved in many neurodegenerative diseases, but recent studies have also demonstrated its pro-oncogenic role: in breast cancer, pro-NGF increases the invasive potential of cells by interacting with the TrkA/Sortilin complex, independently of p75NTR." (PMID 37576898, 2023). "Since these cells comprise 20% to 80% of cells in breast cancer, altogether they are thought to secrete a significant amount of NGF with a significant role on pathological nerve sprouting." (PMID 35163823, 2022). "Contrary to normal breast epithelial cells, both pro-NGF and NGF are synthesized and released by breast cancer cells." (PMID 36354700, 2022). "TrkA and p75NTR are both receptors for NGF that are dysregulated in breast cancer, prostate cancer, and melanoma." (PMID 36499024, 2022). "NGF, through the TrkA receptor, stimulates the migration and invasion of breast cancer MDA-MB-231 and MDA-MB-453 cells." (PMID 35956937, 2022). "Descamps et.al revealed that NGF promoted the proliferation and survival of human breast cancer cells through the activation of TrkA/MAPK axis." (PMID 36522730, 2022). "Our results indicated that NGF also induced TrkA/CD44v3 complex formation in MDA-MB-231 breast cancer cells." (PMID 35346305, 2022). "In breast cancer, the levels of NGF correlate with both the density of tumor innervation and tumor aggression." (PMID 36499024, 2022). "NGF stimulates the invasion of breast cancer MDA-MB-231 cells as a result of the binding of CD44 with the TrkA receptor and the activation of the p115RhoGEF/RhoA/ROCK1 cascade." (PMID 35956937, 2022). "The authors also showed that NGF is biologically active and acts as an autocrine factor for breast cancer development." (PMID 36354700, 2022). "Our study aimed to understand how CD44 and TrkA interact and the consequences of inhibiting this interaction regarding the pro-tumoral effect of NGF in breast cancer." (PMID 35346305, 2022).
breast cancer (continued). "Functionally, the CD44v3 mimetic peptide impairs not only NGF-induced RhoA activation, clonogenicity, and migration/invasion of breast cancer cells in vitro but also tumor growth and metastasis in a xenograft mouse model." (PMID 35346305, 2022). "In conclusion, the evidence reported and discussed in this systematic review demonstrated the pivotal role of pro-NGF, NGF and their receptors’ expression in breast cancer development, proliferation, growth, angiogenesis, migration, invasion and metastasis." (PMID 36354700, 2022). "Due to their proliferative and anti-apoptotic activities, NGF and its receptors seem to also be involved in the invasion and metastasis processes of breast cancer cells." (PMID 36354700, 2022). "We next accessed the cBioPortal tool to evaluate potential correlations between genetic alterations and expressions of the NGF-TrkA/p75NTR axis genes in tumor tissue and prognosis in breast cancer." (PMID 34771423, 2021). "Breast carcinoma cell proliferation is blocked through agonists of cannabinoids receptor of breast carcinoma cells via significant affinity nerve growth factor (Trk) and down-regulation of prolactin (PRL) receptors." (PMID 34205169, 2021). "For example, the study of Hondermarck and colleagues revealed that breast cancer (BC) cells overexpress the nerve growth factor (NGF) in vitro, which induces neurite sprouting from co-cultured sympathetic neurons." (PMID 34503281, 2021). "In human breast cancer samples, levels of NGF correlate with both the level of tumor innervation and tumor aggression." (PMID 33322770, 2020). "Breast cancer cells can stimulate neuronal growth using multiple neurotrophins such as NGF which can be released by Ca2+-mediated exocytosis of NGF-containing vesicles." (PMID 33392191, 2020). "For instance, Pro-NGF also promotes signalling by binding directly to TRKA or P75 (low affinity receptor of NGF)/sortilin in breast cancer and melanoma cells." (PMID 33081077, 2020). "High level of peripheral NGF and BDNF has been proven to be associated with ovarian and breast cancer, polycystic ovarian syndrome (PCOS), and endometriosis." (PMID 33329121, 2020). "Breast cancer, prostate cancer, and melanoma cells grow and spread through the dysregulated expression of TrkA and p75NTR receptors, both of which recognize NGF." (PMID 33322770, 2020). "In breast cancer, NGF/p75NTR affects epithelial markers like keratin 18, keratin 19 and E-cadherin, while promoting mesenchymal markers, like SLUG, to sustain CSCs migratory behavior." (PMID 31812953, 2019). "AEA inhibits the proliferation of breast cancer cells through nerve growth factor (NGF) and prolactin, by downregulating the NGF receptor and prolactin receptor, respectively." (PMID 30987191, 2019). "Pre-clinical murine CIBP studies of osteosarcoma, breast cancer, and prostate cancer have demonstrated that blockage of NGF significantly attenuates pain behaviors and bone destruction mediated by bone tumors." (PMID 29747461, 2018). "The NGF (nerve growth factor) was high correlated with several subtypes of breast cancer, including basal-like breast cancer." (PMID 30139984, 2018). "BEX2 is overexpressed in a subset of primary breast cancers and mediates the inhibition of apoptosis of breast cancer cell lines through nerve growth factor/nuclear factor kappa-light-chain-enhancer of activated B cells (NF-κB)." (PMID 29784063, 2018). "Previously, nerve growth factor induced Gap43 positive nerve fiber sprouting and re-organisation has been reported in a mouse breast cancer bone metastasis model." (PMID 29988965, 2018). "Some types of cancer cells that metastasize to the bone (e.g., breast cancer, prostate cancer) highly express and secrete the neurotrophins nerve growth factor (NGF) and brain-derived neurotrophic factor (BDNF)." (PMID 29747461, 2018).